NSD3 (nuclear receptor binding SET domain protein 3)
Diseases named in the same sentence as NSD3 in open-access papers (continued):
Sharing a sentence is not in itself a finding about the gene and the disease.
cancer (continued). "In this cancer model, H3K36M interacts with NSD2 and NSD3, thus inhibiting their enzymatic activities toward H3K36 methylation." (PMID 41301842, 2025). "During the last few years, NSD3 has been extensively studied in relation to cancer; however, knowledge about the specific roles of the various isoforms in cancer progression remains unknown, and the currently available information focuses on NSD3 function depending on the tumor being studied." (PMID 38256018, 2024). "Together, these results indicate a role for NSD3-BRD4 interaction and suggest therapeutic potential for combined NSD3 PWWP and BET domain inhibition (or degradation) in seemingly unrelated cancer contexts." (PMID 39403928, 2024). "Studies have shown that NSD3 catalyzes H3K36 methylation to transcriptionally activate multiple oncogenic genes, thereby promoting cancer progression." (PMID 34615858, 2021). "The nuclear receptor-binding SET domain 3 (NSD3) catalyzes methylation of histone H3 at lysine 36 (H3K36), and promotes malignant transformation and progression of human cancer." (PMID 34615858, 2021). "In the COSMIC cancer census gene list, the MYC, NSD3 and KAT6A genes on chr8 have been amplified in cancer." (PMID 32512761, 2020). "Other candidates, such as the SPTBN1, NSD3 and CDK14 genes, are able to influence cancer progression through Wnt signaling." (PMID 30102725, 2018). "In particular, we identified the epigenetic regulatory genes NSD3, SETDB1, YEATS4, and BRD4 as putative amplified cancer drivers in several cancer types." (PMID 24874471, 2014). "The cancer driver signatures for SETDB1, YEATS4, NSD3, and BRD4 in TCGA datasets suggests that these genes are important cancer therapeutic targets and potential patient tailoring markers for epigenetics drug discovery efforts." (PMID 24874471, 2014). "Moreover, NSD3 can directly monomethylate EGFR at K721 in the tyrosine kinase domain to activate EGFR-ERK signaling and promote cell cycle progression in this cancer." (PMID 41301842, 2025). "The number of NSD3 inhibitors available for cancer therapy is currently limited, and no drugs targeting NSD3 are available on the market." (PMID 39200173, 2024). "Studies have also shown that NSD3-dependent cancers can be treated by MS9715, which is not available in BI-9321." (PMID 36770884, 2023). "Most importantly, we revealed that intervention of UPR signaling is an actionable therapeutic target for NSD3-amplified LUSC, which might also have considerable benefits in overcoming cancer resistance to immunotherapy." (PMID 36291782, 2022). "As seen in the literature, in our study NSD3 has strong correlation between the CNA amplification content and increasing of expression, a feature showed in many cancer drivers’ genes, which can also suggest the role of NSD3 as a cancer driver." (PMID 32153656, 2020). "While SETDB1 has been validated as a cancer driver in several disease types, NSD3/WHSC1L1 has not been widely investigated for its role in oncogenesis and tumor progression." (PMID 24874471, 2014). "Squamous lung cancers with amplification of the 8p11.23 locus, as defined by NSD3 amplification, do not differ from non-8p11.23-amplified carcinomas in the mean age of patients at presentation, the percentage of patients older than 65 years old or in the sex and race distribution." (PMID 36902501, 2023). "However, the immunological role of NSD3 in driving carcinogenesis has not been systematically studied, especially in large-scale cancer cohorts." (PMID 36291782, 2022). "However, further functional studies are needed to differentiate NSD3 oncogenic activity as dependent or independent of the catalytic domain of the protein, as well as the contribution of each isoform and its clinical significance in cancer progression." (PMID 38256018, 2024).
tumor (36 papers, 2011 to 2025). "Likewise, in HNSCC, the gain-of-function NSD3 mutations that enhance H3K36 methylation increased tumor growth in xenograft models, and the impaired function of NSD3 by H3K36 mutation reduced proliferation of HNSCC cells." (PMID 41301842, 2025). "In contrast, complementation with NSD2 or NSD3 GOF mutations boosted tumor cell growth." (PMID 34083510, 2021). "This study provided the first direct evidence that the methyltransferase activity of NSD3 drives tumor initiation and progression." (PMID 41301842, 2025). "NSD3 has been implicated as a key oncogenic driver in LUSC, but its role in modulating the tumor immune microenvironment remained unclear." (PMID 40586874, 2025). "While the role of NSD3 in tumor immunity remains largely unexplored, several clinical studies suggest its potential importance in reprogramming the tumor immune microenvironment." (PMID 41301842, 2025). "Taken together, our data showed that knockout of NSD3 promoted tumor growth of LUAD in vivo and in vitro." (PMID 39119928, 2024). "The results of Western blot and IHC demonstrated that the expressions of p‐STAT3 and HK2 were promoted in tumor from nude mice with NSD3‐knockout PC9 cells." (PMID 39119928, 2024). "Altogether, these results proved that NSD3 plays a vital role in proliferation, migration, and invasion as a potential tumor suppressor in LUAD." (PMID 39119928, 2024). "As shown, the mRNA expression levels for NSD2 and NSD3 are significantly elevated in tumor samples compared to normal samples, while quantification of protein levels reveal that NSD3 is upregulated in tumor samples." (PMID 37062069, 2023). "Next-generation sequencing revealed a NUT::NSD3 gene fusion corresponding to (“speckled-type”) immunopositivity of NUT in the tumor cells." (PMID 37118352, 2023). "Recent studies have shown that NSD3-induced histone methylation is functionally involved in tumor initiation and progression by facilitating the transactivation of oncogenic signaling, such as NOTCH, MYC, and mTORC1." (PMID 36291782, 2022). "The majority of these cases manifested a tumor with chromosomal translocation, which forms the BRD4-NUT fusion oncogene (n = 16), BRD3-NUT (n = 4), NSD3-NUT (n = 3), NUT-variant (n = 1), CHRM5-NUTM1 (n = 1) and other NUTM1 rearrangements (n = 5)." (PMID 36290813, 2022). "To investigate the possible correlation between NSD3 gene amplification and anti-tumor immunity, we sought to evaluate the immune landscapes within NSD3-amplified LUSC samples using a multi-faceted approach." (PMID 36291782, 2022). "Further molecular characterization revealed the potential internal links between the unfolded protein response and the “cold” tumor immune microenvironment of NSD3-amplified LUSC." (PMID 36291782, 2022). "As expected, a similar suppressive anti-tumor immunity was observed in LUSC patients with high protein levels of NSD3." (PMID 36291782, 2022). "In vivo, H3K36me2 and NSD3-dependent genes were significantly decreased in PanCa-1 xenograft tumor tissues with NSD3 shRNA AAV injection." (PMID 34615858, 2021). "Two recent publications shed more light on how altered NSD3 activity promotes tumor development and growth." (PMID 34440470, 2021). "Clinically, high NSD3 expression correlates with tumor recurrence by distant metastasis." (PMID 41301842, 2025). "Given that IRF3 is a key component for recognition of tumor antigen during the innate immunity, this finding raises the possibility that NSD3 may play a critical role in tumor immune surveillance." (PMID 41301842, 2025). "Correspondingly, the expression of NSD3 negatively correlated with N and tumor stages." (PMID 39119928, 2024). "The patient’s exceptionally long survival could be due to NSD3 as the fusion partner, aided by the initial small tumor size and young patient age." (PMID 39200173, 2024). "Together, these results suggested that NSD3 functions as a tumor suppressor in LUAD." (PMID 39119928, 2024).
tumor (continued). "Finally, we performed multivariate analysis and discovered that both NSD3 expression (HR = 2.917, p = 0.018) and tumor grade (HR = 3.778, p = 0.005) were informative as prognostic markers for clinical outcome in patients." (PMID 37062069, 2023). "We find that tumor tissues express high levels of NSD3 compared to paired normal tissues." (PMID 37062069, 2023). "More valuable, our data imply that either directly targeting NSD3 or intervention of UPR signaling might be a promising therapeutic rationale to boost anti-tumor immunity and improve the immunotherapy response." (PMID 36291782, 2022). "Therefore, future studies will be interesting to explore how the UPR contributes to the NSD3-driven “cold” tumor immune microenvironment." (PMID 36291782, 2022). "Furthermore, genetic knockout of NSD3 specifically led to a potent anti-tumor effect in NSD3-amplified LUSC cell lines." (PMID 36291782, 2022). "Given the enormous enrichment of the UPR in NSD3-amplified tumors and the tight junction between UPR signaling and anti-tumor immunity, we sought to determine whether the UPR is associated with the suppressive immunological features of NSD3-amplified LUSC." (PMID 36291782, 2022). "Finally, the molecular and functional characteristics of NSD3 in different tumor types according to the current research are summarized." (PMID 34440470, 2021). "In vivo, NSD3 shRNA AAV injection potently inhibited PanCa-1 xenograft tumor growth in nude mice." (PMID 34615858, 2021). "NSD3 depletion elicited prominent inhibition of tumor growth in these PDX models." (PMID 34083510, 2021). "Amplification of oncogenes KAT6A and NSD3 (previously known as WHSC1L1) in this region may be involved in driving tumor cell growth and carcinogenesis." (PMID 28957377, 2017). "They propose that BET inhibition may counteract the effect of NSD3 on tumor growth." (PMID 38256018, 2024). "We speculate that this could alleviate negative signaling pathways that block tumor proliferation.Specific to NSD3, this gene encodes three isoforms, as follows." (PMID 37062069, 2023). "Interestingly, ssGSEA (GSVA) showed that the hyperactivity of NSD3 further accelerated the immune-desert phenotype in the tumor, as indicated by the reduced infiltration of several immune cell types (e.g., activated DCs, B cells, and mast cells) and repressed activities of the type II-IFN response." (PMID 36291782, 2022). "Depleting NSD3 could significantly restrain tumor growth and extend the lifespan of PSC mice." (PMID 34083510, 2021). "In MCF7 cells, NSD3 overexpression induces EMT and invasion, while NSD3 knockdown in MDA-MB-231 cells reverses EMT, suppresses migration and invasion, and reduces tumor metastasis in vivo." (PMID 41301842, 2025). "The short isoforms of NSD2 and NSD3, which lack the catalytic SET domain, retain potent tumor-promoting capabilities by functioning as chromatin scaffolds, transcriptional adaptors, and protein interaction hubs." (PMID 41301842, 2025). "NSD3 (WHSC1L1), a histone H3K36 methyltransferase, acts as a key oncogenic driver of the 8p11–12 amplicon in LUSC and promotes tumor progression." (PMID 41303594, 2025). "The tumor from the mouse injected with NSD3‐knockout PC9 cells grew faster and more extensive than the tumor of control PC9 cells." (PMID 39119928, 2024). "Meanwhile, the levels of Ki‐67 in tumor from nude mice with NSD3‐knockout PC9 cells were higher than in the control group, suggesting that the low levels of NSD3 are positively correlated with a stronger proliferation ability." (PMID 39119928, 2024). "Novel targets such as nuclear receptor-binding SET domain protein 3 (NSD3), lysine methyltransferase 2 D (KMT2D), and ubiquitin-specific peptidase 28 (USP28), are related to tumor microenvironment (TME) and immune cells." (PMID 39544292, 2024). "Preclinical studies have identified both oncogenic and tumor-suppressing properties across NSD1, NSD2, and NSD3 within the context of HNSCC." (PMID 36360250, 2022).
tumor (continued). "Generally, we found that NSD3-amplified tumors exhibited lower stromal, immune, and ESTIMATE scores but a higher tumor purity than the wild-type tumors." (PMID 36291782, 2022). "Ablation of nuclear receptor binding SET domain protein 3 (NSD3), frequently upregulated in human LUSC, significantly extended animal survival and reduced tumour size in this model, indicating an oncogenic role for this methyltransferase in LUSC80." (PMID 34354223, 2021). "NSD3-amplified LUSC exhibits a non-inflamed tumor immune microenvironment with a worse immunotherapy outcome." (PMID 41301842, 2025). "Within this amplicon, NSD3 has emerged as a primary driver oncogene, suggesting that NSD3 amplification is not a mere bystander event but instead drives functional alterations that promote tumor initiation and progression." (PMID 41301842, 2025). "Together, these data confirm a pivotal oncogenic role for NSD3 in LUSC tumorigenesis and indicate that NSD3 might participate in regulating anti-tumor immunity." (PMID 36291782, 2022). "We revealed that NSD3-amplified LUSC presents a non-inflamed tumor immune microenvironment (TIME) state in multiple independent LUSC patient cohorts." (PMID 36291782, 2022). "Therefore, further studies comparing genomically profiled NC tumor cell lines with BRD3, NSD3, or other gene fusion characteristics are needed." (PMID 35681742, 2022). "His tumour was found to be positive for NUT expression by IHC and to harbour NSD3-NUT fusion." (PMID 33311588, 2021). "Given that NSD1 and NSD2 have been linked to various aspects of HPV- HNSCC, including epigenetic alterations, immune status of the tumor, and predicting patient outcome at specific subsites, we investigated the roles of NSD1 and its two paralogs NSD2 and NSD3 in HPV+ HNSCC." (PMID 33588906, 2021). "Notably, the responding patients with NC had tumours harbouring BRD3-NUT and NSD3-NUT fusions, respectively." (PMID 33311588, 2021). "We also investigated the relationship between the levels of expression of NSD1, NSD2, or NSD3 with tumor-infiltrating lymphocytes (TILs) in either the HPV+ or HPV- HNSCC samples and whether expression of NSD1, NSD2, or NSD3 correlated with overall survival." (PMID 33588906, 2021). "We selected the physical interaction of MYC with NSD3 for validation, and uncovered a potential positive regulatory function for NSD3 in activating MYC, implicating the BRD4-NSD3-MYC pathway as a potential target for interrogating MYC-driven tumours." (PMID 28205554, 2017). "Additionally, another study revealed that LUSC with NSD3 amplification presented a non-inflamed tumor immune microenvironment state in LUSC patient cohorts." (PMID 40586874, 2025). "In addition to the 8 representative PKMTs with tumor suppressor activity, PRDM16, MLL2, MLL4, SET domain bifurcated histone lysine methyltransferase 1 (SETDB1), SETD3, NSD1, NSD3, DOT1L, SUV39H1, and SUV39H2 have also been suggested to possess tumor suppressor activity." (PMID 38036730, 2023).
hematological cancer (2 papers, 2024 to 2025). "In addition, MS9715, but not BI-9321, depleted cellular NSD3 and suppressed c-Myc-associated genes in NSD3-dependent hematological cancer cells." (PMID 38389844, 2024). "MS9715 effectively inhibited NSD3-dependent hematological cancer cells and suppressed NSD3- and cMyc-driven oncogenic pathways more effectively than BI-9321 alone, recapitulating the effects of NSD3 knockout." (PMID 40586874, 2025).
bacterial diseases (1 paper, 2023). "Potato lines that carried the nsd3 gene demonstrated higher resistance levels to a complex of fungal and bacterial diseases in laboratory and field experiments." (PMID 37175769, 2023).
NSD3 also shares sentences with these, for which no sentence is quoted: head and neck squamous cell carcinoma (5 papers); bladder cancer (4); squamous cell carcinoma (3); Lynch syndrome (2); melanoma (2); multiple myeloma (2); Wolf-Hirschhorn syndrome (2); acute lymphoblastic leukemia (1); adenocarcinoma (1); anaplastic thyroid carcinoma (1); blood cancer (1); Epileptic encephalopathy (1); glioma (1); kidney cancer (1); neuroblastoma (1); neurological diseases (1); non-small cell lung carcinoma (1); pancreatic adenocarcinoma (1); Parkinson’s (1); prostate carcinoma (1); rectal tumor (1); schizophrenia (1); Strabismus (1); Stroke (1); Weaver syndrome (1).